AMT (aminomethyltransferase)
Description:
The glycine cleavage system catalyzes the degradation of glycine.
Synonyms: GCVT; GCST; NKH; GCE; GCE2
Tractability: Small molecule: a structure with a bound ligand is known; it has a high-quality binding pocket. PROTAC: its protein half-life has been measured.
Gene: Protein-coding gene on chromosome 3 (49,416,778 to 49,422,685, reverse strand). Ensembl gene ENSG00000145020.
Subcellular location: Mitochondrion
Subcellular location (Human Protein Atlas): Mitochondria; Nucleoplasm
Pathways (Reactome):
Metabolism: Glycine degradation
Gene Ontology:
Molecular function: aminomethyltransferase activity
Biological process: glycine decarboxylation via glycine cleavage system; glycine catabolic process
Cellular component: mitochondrion; mitochondrial matrix; glycine cleavage complex
Genetic constraint (gnomAD): Loss-of-function variants: 24 observed, 41.95 expected, observed/expected ratio (o/e) 0.57, 90% interval 0.41 to 0.81. The upper end of that interval is the gene's LOEUF score, 0.81, which puts it in group 3 of 6, group 1 being the genes least tolerant of losing a copy. Missense variants: 501 observed, 566.25 expected, observed/expected ratio (o/e) 0.88, 90% interval 0.82 to 0.95. Synonymous variants: 210 observed, 224.5 expected, observed/expected ratio (o/e) 0.94, 90% interval 0.83 to 1.05.
Gene-disease validity (ClinGen):
ClinGen rates the evidence that AMT causes each of these diseases.
glycine encephalopathy (autosomal recessive): Definitive. Glycine encephalopathy (GE) is an inborn error of glycine metabolism characterized by accumulation of glycine in body fluids and tissues, including the brain, resulting in neurometabolic symptoms of variable severity.
Homologues: Orthologues: chimpanzee AMT (99% identical), macaque AMT (97% identical), dog AMT (90% identical), pig AMT (90% identical), mouse Amt (89% identical), rat Amt (89% identical), rabbit AMT (88% identical), guinea pig AMT (68% identical), tropical clawed frog amt (67% identical), zebrafish amt (65% identical), Caenorhabditis elegans gcst-1 (51% identical), Drosophila melanogaster CG6415 (51% identical). Paralogues in human: DMGDH (28% identical), SARDH (27% identical), PDPR (24% identical), L2HGDH (12% identical), FOXRED1 (8% identical), YPEL3 (8% identical), YPEL1 (7% identical), YPEL2 (7% identical), YPEL4 (7% identical), YPEL5 (5% identical).
Diseases named in the same sentence as AMT in open-access papers:
AMT is named in the same sentence as 28 diseases in open-access papers, as found by Europe PMC text mining. Sharing a sentence is not in itself a finding about the gene and the disease. The quoted sentences say what the papers report.
glycine encephalopathy (8 papers, 2014 to 2024). "AMT mutations are associated with glycine encephalopathy—a rare condition associated with brain abnormality and learning difficulties among other traits." (PMID 33795730, 2021). "Glycine encephalopathy is associated with mutation in AMT, GLDC, and GCSH genes." (PMID 25029527, 2014). "Mutation of AMT or GLDC, encoding the GCS components aminomethyltransferase and glycine decarboxylase, can cause malformations of the developing CNS (neural tube defects (NTDs) and ventriculomegaly) as well as a post-natal life-limiting neurometabolic disorder, Non-Ketotic Hyperglycinemia." (PMID 33569080, 2021). "Nonketotic hyperglycinemia (NKH) is a rare, autosomal recessive metabolic disorder usually associated with mutations in genes AMT, GLDC or GCSH involved in the glycine cleavage complex." (PMID 39323869, 2024). "Non-ketotic hyperglycinemia (NKH) is an ultra-rare (incidence 1/76,000 births) genetic, neurometabolic disorder caused by deficient enzyme activity of the glycine cleavage enzyme (GCE) (EC 1.4.4.2) due to mutations in GLDC encoding the P-protein or AMT encoding the T-protein." (PMID 38589924, 2024). "In addition, approximately 5% of patients with enzyme-proven glycine encephalopathy do not have a pathogenic variant in GLDC, AMT or GCSH genes; these cases therefore represent a variant form of NKH." (PMID 29304759, 2018).
autism (2 papers, 2013 to 2022). Persistent deficits in social interaction and communication and interaction as well as a markedly restricted repertoire of activity and interest as well as repetitive patterns of behavior. "Likewise, mutations in genes either encoding GlyRs, KCC2, or the amino methyltransferase enzyme (AMT) involved in glycine degradation, were reported in patients affected by autism, supporting the glycine role in neurogenesis." (PMID 36188468, 2022). "Moreover, mutations in genes encoding either the GlyR alpha 2 subunit or the aminomethyltransferase enzyme (AMT), which is an important factor involved in the degradation of glycine, have been found in patients affected by autism." (PMID 24155690, 2013).
colon cancer (1 paper, 2025). "In tumor tissue of right- compared to left-sided colon cancer, there was a lower gene expression of AMT (p < 0.01), GGH (p < 0.0001), PCFT (p < 0.05), and RFC-1 (p < 0.01)." (PMID 39998667, 2025).
dyslexia (1 paper, 2025). A learning disorder characterized by an impairment in processing written words. "Four genes – SORCS3, TCTA, TRAIP and AMT – shown to be pleiotropic had previously been associated with dyslexia and ADHD in individual GWAS studies and are very strong pleiotropic candidate genes." (PMID 39009701, 2025).
glioma (1 paper, 2024). A benign or malignant brain and spinal cord tumor that arises from glial cells (astrocytes, oligodendrocytes, ependymal cells). "The results indicated that AMT, AS3MT, EGFR, NICN1, and POLR3K exhibited significant sex differences in expression within glioma tissues." (PMID 39722126, 2024).
Hepatic steatosis (1 paper, 2023). Steatosis is a term used to denote lipid accumulation within hepatocytes. "The AMT gene is associated with “hepatic steatosis” and “NAFLD”, and the canonical pathway’s “PI3K/AKT signaling”." (PMID 37511368, 2023).
Hyperglycemia (1 paper, 2018). An increased concentration of glucose in the blood. "The antihyperglycemic activity of AmT was indicated in vivo by the control of postprandial hyperglycemia in normoglycemic mice subjected to glucose overload, and this activity was similar to that of metformin." (PMID 29870561, 2018).
lung carcinoma (1 paper, 2021). "SLC25A42, AMT, and IVD genes have also been found in other prognostic models of lung cancer." (PMID 34539973, 2021). "In addition, our model screened several genes that have not been studied in the field of lung cancer but are closely related to the prognosis of LUAD patients, such as SLC25A42, AMT, and IVD, which provides a basis for future research on the mechanism of lung cancer." (PMID 34539973, 2021).
Obesity (1 paper, 2024). Accumulation of substantial excess body fat. "We envisage a scenario in which obesity-associated meta-inflammation impairs AMT/ATR activation with dysregulated downstream DNA damage repair." (PMID 39092995, 2024).
tumor (4 papers, 2023 to 2025). "The expression of AMT was lower in tumors compared to mucosa, suggesting less AMT activity in the mitochondria of tumor tissue." (PMID 39998667, 2025). "Elevated promoter methylation events involved 168 genes with reduced tumor expression, and it was notable that promoter hypermethylation of AMT, CCL21 and SPARCL1 were detected in the vast majority of tumors." (PMID 39104720, 2024). "Depending on tumor location, the expression of ABCC3, AMT, GGH, and RFC-1 in mucosa, as well as the tumoral expression of AMT, GGH, PCFT and RFC-1 differed." (PMID 39998667, 2025). "As depicted by the results, there was no marked difference in PTGS1 and AMT expression between tumor and normal cell lines." (PMID 38454278, 2024). "The RT-qPCR analysis showed that PLCE1, ST8SIA1, ST3GAL5, and GBA2 were aberrantly regulated between the tumor and nontumor cell lines, while the results of PTGS1 and AMT showed no significance." (PMID 38454278, 2024).
AMT also shares sentences with these, for which no sentence is quoted: infection (3 papers); cancer (2); biotinidase deficiency (1); brain disorder (1); breast carcinoma (1); co-infection (1); creatine transporter deficiency (1); Crohn disease (1); Fanconi anemia (1); Gaucher disease (1); giardiasis (1); metabolic disorder (1); Molybdenum cofactor deficiency (1); Parkinson disease (1); postmenopausal osteoporosis (1); prostate carcinoma (1); pyridoxine-dependent epilepsy (1); Ventriculomegaly (1).